IL1B (interleukin 1 beta)
Diseases named in the same sentence as IL1B in open-access papers (continued):
Sharing a sentence is not in itself a finding about the gene and the disease.
Kleefstra syndrome (1 paper, 2025). A genetic disorder characterized by intellectual disability, childhood hypotonia, severe expressive speech delay and a distinctive facial appearance with a spectrum of additional clinical features. "Furthermore, insights from a Kleefstra syndrome mouse model illuminated elevated expression of specific inflammatory genes, including IL-1b, alongside an increase in activated microglial cells within the brain, thereby underscoring the presence of cerebral inflammation in these patients." (PMID 40400398, 2025).
Large vessel vasculitis (1 paper, 2021). A type of vasculitis (inflammation of blood vessel walls) affecting large arteries such as the aorta and branches of the aorta. "IL-1β, IL-6 and TNF-α produced by macrophages amplify the inflammatory response and lead to the large vessel vasculitis which including fever, weakness, anorexia, weight loss and acute phase response." (PMID 34429489, 2021).
laryngeal tumors (1 paper, 2024). "Among these, Interleukin (IL)-6 (P ═ 0.021) was highly expressed in laryngeal tumors, and the expression levels of IL-1β (P ═ 0.008), IL-6 (P ═ 0.005), and IL-8 (P ═ 0.05) were higher in patients with poorly differentiated laryngeal tumors." (PMID 38920620, 2024).
lepromatous leprosy (1 paper, 2020). A chronic communicable infection which is a principal or polar form of leprosy. "NLRP3 inflammasome’s immunohistochemical strong expression score is ahallmark of the Lepromatous Leprosy - The immunohistochemicalexpression of NLRP3, caspase-1, caspases-4/5, IL-1β, IL-6, and IL-18 between thegroups presented statistically significant differences in the scores." (PMID 32130367, 2020).
liver hemangioma (1 paper, 2025). A hemangioma arising from the liver. "In vivo, an orthotopic liver hemangioma mouse model was established, and RFA was performed to evaluate the levels of IL-1β and IL-18, wet-to-dry lung ratio, and inflammation score." (PMID 41280917, 2025).
lumbar spinal stenosis (1 paper, 2018). A spinal stenosis that involves the lumbar region of vertebral column. "Clinical studies have shown increased levels of IL-1β in human facet joint tissue from patients undergoing surgery for lumbar spinal stenosis and disc herniation." (PMID 30250404, 2018).
lymphoproliferative disorder (1 paper, 2014). "Hypothetically, the presence of mutant (myeloid) cells in the bone marrow of SchS patients produces high local concentrations of IL-1β and IL-6, facilitating the development of a lymphoproliferative disorder." (PMID 25905009, 2014).
mantle cell lymphoma (1 paper, 2023). Mantle cell lymphoma is a rare form of malignant non-Hodgkin lymphoma affecting B lymphocytes in the lymph nodes in a region called the ``mantle zone''. "For instance, β-catenin can inhibit the nuclear transcription of NF-κB and can, therefore, suppress the production of cytokines, such as IL-6, IL-18, and IL-1β, in mantle cell lymphoma (MCL)." (PMID 37189739, 2023).
mastocytosis (1 paper, 2018). A clonal myeloproliferative neoplasm characterized by the proliferation and accumulation of neoplastic mast cells in one or multiple organs or organ systems. "A hypothetical model for generation of fatigue in mastocytosis is therefore thatactivated MCs outside the brain release IL-1β, IL-6, TNF-α, and other bioactivemolecules that pass the BBB and activate neuronal cells as well as microglia." (PMID 30350746, 2018).
melasma (1 paper, 2025). "We consistently observed that AOPT‐LTL treatment significantly reduced mast cell infiltration and the release of pro‐inflammatory cytokines (TNF‐α, IL‐1β, IL‐6) and the expression of key enzymes regulating inflammatory mediators (iNOS, COX‐2) in a guinea pig model of melasma." (PMID 40916844, 2025).
membranous glomerulonephritis (1 paper, 2013). A slowly progressive inflammation of the glomeruli characterized by immune complex deposits at the glomerular basement membrane, resulting in a thickened membrane, and nephrotic syndrome. "This study is the first to report the effects of skimmin, a major constituent present in H. paniculata, on IL-1β and IL-6 protein expression in membranous glomerulonephritis." (PMID 23990847, 2013). "Together, these results suggested that changes in IL-6 or IL-1β concentrations are closely related to the pathogenesis of membranous glomerulonephritis." (PMID 23990847, 2013).
meningococcal meningitis (1 paper, 2015). "However, the severity of meningococcal meningitis is directly correlated with the production of IL-1β, TNF-α, IL-6 and IL-8." (PMID 26316174, 2015).
mesangial sclerosis (1 paper, 2019). "IL-1β blockade did not significantly affect interstitial fibrosis as detected by aSMA staining or mesangial sclerosis as detected by Sirius red staining, though anti-IL-1β treatment reduced αSMA but not collagen 1alpha1 gene expression." (PMID 31191559, 2019).
middle ear infection (1 paper, 2024). "Their mRNA expression was found to be significantly elevated in CSOM (42.1 ± 13.3 for NLRP3, 199.2 ± 73.4 for IL-1β) compared to control (non-CSOM) cochleae (1.91 ± 0.91, p = 0.018 for NLRP3; 2.83 ± 1.55, p = 0.032 for IL-1β) at 7 days following middle ear infection." (PMID 39277762, 2024).
minimal-change nephrotic syndrome (1 paper, 2022). "In kidney biopsy analyses, increased glomerular and tubulointerstitial IL-1β protein was found in DKD compared to non-kidney disease control subjects, and IL-18 protein showed a stronger expression in tubular cells of diabetic patients compared to patients with minimal change nephrotic syndrome." (PMID 35204131, 2022).
mitral valve regurgitation (1 paper, 2017). "With regard to IL-1β, we observed significant negative correlations between this cytokine levels and both LV mass (ρ=-0.21, p=0.037) and the presence of moderate-severe mitral valve regurgitation (ρ=-0.18, p=0.023)." (PMID 28212578, 2017).
morphine dependence (1 paper, 2024). Strong dependence, both physiological and emotional, upon morphine. "Furthermore, MDD, morphine dependence, and nicotine dependence share pro-inflammatory cytokines interleukin 6 (IL6), interleukin 1B (IL1B), and tumor necrosis factor (TNF) with progeria syndrome." (PMID 38926475, 2024).
muscle atrophy (1 paper, 2022). The loss of muscle tissue due to inactivity or disease. "We also discovered that inflammation-related genes (TNF-, IL-6, and IL-1b) showed no changes even after 5 weeks of EVs-Cas9-29b therapy in IMO- and Den-induced muscle atrophy which is coincidentally the endpoint of the treatments." (PMID 35761332, 2022).
Myocardial necrosis (1 paper, 2022). Irreversible damage to heart tissue (myocardium) due to lack of oxygen after a heart attack (myocardial infarction). "IL-1β and IL-6 have been demonstrated as proinflammatory cytokines and were associated with myocardial necrosis." (PMID 35928492, 2022).
myoma (1 paper, 2025). "Furthermore, there was a significant positive correlation between the concentration of IL-1β and reduced NF-κβ levels in the center of the myoma." (PMID 40672945, 2025).
myxoma (1 paper, 2024). A benign soft tissue neoplasm characterized by the presence of spindle and stellate cells, lobulated growth pattern, and myxoid stroma formation. "Macrophages in myxoma were associated with the upregulation of NFKB1, PDGFC, and IL1B, as well as the downregulation of ATP5PB, HSPB1, and IFI27." (PMID 39090109, 2024).
nasopharyngeal squamous cell carcinoma (1 paper, 2025). A squamous cell carcinoma that arises from the nasopharynx. "Besides, the overexpression of IL-1β shown poor prognosis of patients with oral and nasopharyngeal squamous cell carcinoma." (PMID 40839565, 2025).
nephrosclerosis (1 paper, 2023). Hardening of the kidney due to infiltration by fibrous connective tissue (fibrosis), usually caused by renovascular diseases or chronic hypertension. "In order to establish an in vitro model of activated fibroblasts, which may mimic the subpopulation of renal fibroblasts of our in vivo experimental nephrosclerosis model, we stimulate rat renal immortalized fibroblasts from a commercially available cell line (NRK-49F) with IL-1β + AngII." (PMID 37633958, 2023).
neuro-degenerative diseases (1 paper, 2023). "For example, in many neuro-degenerative diseases, typically characterized by an elevated inflammation state, the increase in both intra- and extracellular Glu might be induced by high levels of pro-inflammatory cytokines, especially IL-1β and TNF-α." (PMID 37854352, 2023).
Neurodevelopmental delay (1 paper, 2020). "For controls, we found higher average levels of a subset of cytokines including IL-4, IL-1β, PlGF, GM-CSF, SAA, IL-15, TNF-β, VEGF-D, IL-12p70, Tie-2, IL-2, IL-17α, IFN-ɣ, and IL-10 in children with neurodevelopmental delay (C/ND), compared to that of their typically developing (C/TD) counterparts." (PMID 31992316, 2020).
Neurofibrillary tangles (1 paper, 2021). Pathological protein aggregates formed by hyperphosphorylation of a microtubule-associated protein known as tau, causing it to aggregate in an insoluble form. "Tellingly, IL-1β and IL-6 in the brain of AD patients restrain the function of cholinergic systems and activate Aβ aggregation, leading to the accumulation of neurofibrillary tangle (NFT)." (PMID 34065080, 2021).
neurosyphilis (1 paper, 2024). Infection of the brain or spinal cord by Treponema pallidum. "The neuroinflammatory response in neurosyphilis involves the activation of microglia, which release pro-inflammatory cytokines such as tumor necrosis factor-alpha (TNF-α), interleukin-1 beta (IL-1β), and interleukin-6 (IL-6)." (PMID 39728746, 2024).
neurotoxicity (1 paper, 2025). Toxicity that causes injury to the central or peripheral nervous system or damages its function. "Neurotoxicity is a pathological phenomenon seen in neuroHIV that was also observed through transfer of cell-free CM from Ephb2 activated microglia onto neurons, which our data suggest is a consequence of the assortment of pro-inflammatory secreted factors (IL-6, CXCL10, TNFα, IL-1β etc.)." (PMID 40588746, 2025).
nevus (1 paper, 2025). Nevus (or naevus, plural nevi or naevi, from nævus, Latin for "birthmark") is the medical term for sharply circumscribed[1] and chronic lesions of the skin or mucosa. "Venetoclax effectively induces apoptosis in GCMN cells, with a critical role for neutrophils and the IL1β pathway in mediating immune responses and nevus regression." (PMID 40374605, 2025).
Newcastle disease (1 paper, 2020). A condition caused by infection by the Newcastle disease virus, which may be characterized by conjunctivitis, respiratory illness, and diarrhea. "Therefore, exploring the mechanisms underlying NDV-induced IL-1β expression can aid in further understanding the pathogenesis of Newcastle disease." (PMID 32293543, 2020).
Niemann-Pick disease (1 paper, 2025). A group of inherited, severe metabolic disorders in which sphingomyelin accumulates in lysosomes in cells. "In contrast, reduced levels of IL-1β were found in the brain of acid sphingomyelinase knockout mice, a mouse model of the infantile form of Niemann Pick disease (type A), which is likely caused by a blockage of IL-1β release by astrocytes." (PMID 40270964, 2025).
nocardiosis (1 paper, 2022). Nocardiosis is a local (skin, lung, brain) or disseminated (whole body) acute, subacute, or chronic bacterial infection. "N. seriolae could significantly change the expression levels of mx, perforin, tgm3, il-1β and other genes in the kidney, liver, and spleen of diseased hybrid snakeheads, indicating that these genes have the potential to be developed as biomarkers for fish nocardiosis." (PMID 35154103, 2022).
obstructive jaundice (1 paper, 2024). A finding indicating increased bilirubin levels in the blood and urine, due to intrahepatic or extrahepatic obstruction of the biliary system. "Their study identified a panel of IL-8, interferon gamma-induced protein 10 (IP-10), IL-1b, and platelet-derived growth factor (PDGF) as having a more significant impact on classifying patients with PDAC and benign disease in the presence of obstructive jaundice compared to CA19-9." (PMID 39457656, 2024).
occupational asthma (1 paper, 2025). Asthma attacks caused, triggered, or exacerbated by OCCUPATIONAL EXPOSURE. "In contrast, spores and fragments < 4.7 μm can bypass mucociliary clearance and deposit in the alveoli, triggering oxidative stress and neutrophilic inflammatory responses characterized by IL-1β/IL-8 release, which are associated with phenotypes like occupational asthma." (PMID 41472059, 2025).
oesophageal stricture (1 paper, 2021). "IL-1β and TNF-α, two major pro-inflammatory cytokines that induce oesophageal stricture, were significantly suppressed by cell sheet engraftment." (PMID 34315989, 2021).
opisthorchiasis (1 paper, 2018). Infection with flukes of the genus Opisthorchis. "This study aimed to investigate risk factors for ICC with a focus on opisthorchiasis and polymorphisms of proinflammatory cytokines (IL-1β and TNF-α)." (PMID 30139338, 2018).
Optic neuropathy (1 paper, 2007). "The lack of an association of the common polymorphisms of the IL-1β with NTG in Chinese population suggests this factor may not have a significant role in the pathogenesis of the optic neuropathy." (PMID 17563722, 2007). "IL-1β may not have a significant role in the pathogenesis of the optic neuropathy." (PMID 17563722, 2007).
oral cavity cancer (1 paper, 1993). A primary or metastatic malignant neoplasm involving the oral cavity. "We studied the production of interleukin 1 beta (IL-1 beta) and interleukin 6 (IL-6) by peripheral blood monocytes from 22 patients with HNSC (12 larynx and ten oral cavity cancers) in comparison with monocyte cytokine production of age-matched healthy subjects." (PMID 8353036, 1993).
organic acidemia (1 paper, 2013). "Considering that IL-1β can also inhibit glutamate uptake in astrocytes and increase its glial release possibly via TNF-α production, the increase of pro-inflammatory cytokines may result in elevated extracellular glutamate levels and toxicity in this model of organic acidemia." (PMID 24205200, 2013).
oro-pharyngeal cancers (1 paper, 2013). "We also show that high IL1B is associated with increased overall survival in a cohort of patients with oro-pharyngeal cancers." (PMID 23867201, 2013). "IL1B inhibited invasion in our model system, so to determine if the levels of IL1B in oro-pharyngeal cancers had a protective effect, we examined the mRNA levels of IL1B by real-time PCR in matched non-tumour and tumour tissue from 22 oro-pharyngeal cancers." (PMID 23867201, 2013).
Orofacial dyskinesia (1 paper, 2023). "Increased (in comparison to control animals who were only exposed to the vehiculum used) striatal levels of IL-1β were invariably found in rodent models of haloperidol-induced orofacial dyskinesia." (PMID 37810262, 2023). "Hence, striatal IL-1β levels correlate with the presence of orofacial dyskinesia but are probably not primary in this regard." (PMID 37810262, 2023).
otosclerosis (1 paper, 2015). Formation of spongy bone in the labyrinth capsule which can progress toward the stapes (stapedial fixation) or anteriorly toward the cochlea leading to conductive, sensorineural, or mixed hearing loss. "However, we observed that the TNF-α and IL-1β expression levels were significantly higher in tissue samples obtained from patients with otosclerosis as compared to the control, t (<1.96)." (PMID 24676726, 2015). "IL-1β transcript was detected in 46 virus-positive (93.8 %) and in 10 virus-negative (83.3 %) stapes obtained from patients with otosclerosis OPG transcript was detectable in only 18 virus-positive (36.7 %) and in 5 virus-negative (41.7 %) patient’s stapes." (PMID 24676726, 2015). "In our study, we analyzed the expression level of proinflammatory cytokines (TNF-α, IL-1β), OPG and the presence of measles virus RNA in fragments of the stapes (superstructure and part of the otosclerotic changed footplate) removed during stapedotomy performed in patients with otosclerosis." (PMID 24676726, 2015).
pancreatic adenocarcinoma (1 paper, 2010). "Moreover, when studying the adhesion of pancreatic adenocarcinoma cells to hepatic sinusoidal endothelial cells, ST3Gal III and SLex overexpressing C31 cells demonstrated an enhanced ability to adhere to IL-1β stimulated HSE cells compared with controls." (PMID 20824144, 2010).
PAPA syndrome (1 paper, 2021). "Additionally, neutrophils from patients with PAPA syndrome undergo NETosis in the presence of recombinant IL-1β, whereas those from healthy subjects do not, suggesting that PAPA neutrophils are primed to respond to IL-1β." (PMID 34944704, 2021).
paracoccidioidomycosis (1 paper, 2021). A systemic fungal infection caused by Paracoccidioides brasiliensis that is most often seen in immunocompromised patients. "Higher intracellular protein expression of NLRP3, CASP-1, ASC, and IL-1β and increased priming in mRNA levels of NLRP3 inflammasome genes in monocytes isolated from patients with a chronic form of paracoccidioidomycosis was also reported in comparison to controls." (PMID 33668671, 2021).
pasteurellosis (1 paper, 2021). Infections with bacteria of the genus pasteurella. "Therefore, in this study we have investigated the impact of vitamin C on the production of pro-inflammatory cytokines (IL-1β, IL-6, IL-12p40, IFN-γ, and TNF-α) in lambs naturally infected by pneumonic pasteurellosis." (PMID 34944151, 2021). "Wilks’ lambda test for drug × time interaction, p < 0.0001) of vitamin C, a major water-soluble vitamin in normalization the pro-inflammatory cytokines (IL-1β, Il-6, IFN-γ, and TNF-α) when used in combination with tulathromycin in lambs with pneumonic pasteurellosis." (PMID 34944151, 2021). "Moreover, elevated expression of IL1-β and TNF-α were detected in the respiratory airways and lung lesions of calves with pneumonic pasteurellosis." (PMID 34944151, 2021).
Pca (1 paper, 2019). "In PCa, high immunostaining of IL-1β has been associated with recurrence, and high IL-1β levels have been found in tumours and sera of patients with advanced disease." (PMID 31480312, 2019). "On the other hand, tumour cells themselves secrete several pro-inflammatory cytokines, including interleukin (IL)-6 and IL-1β, strongly implicated in PCa progression." (PMID 31480312, 2019). "The result is in agreement with the high IL-1β levels found in tissue and serum of Pca patients with advanced disease." (PMID 31480312, 2019). "IL-1β, together with NF-κB, has already been associated with the progression of PCa." (PMID 31480312, 2019). "IL-1β, one of the most abundant pro-inflammatory cytokines of the tumour microenvironment, and NLRP3-inflammasome activation have been involved in tumourigenesis and progression of PCa." (PMID 31480312, 2019). "With the knowledge that IL-1β, NLRP3-inflammasome and EVs have a pivotal role in the establishment of tumour microenvironment, the contribution of EVs released from advanced-stage PCa cells on the behaviour of microenvironment-residing or infiltrating non-cancerous cells has never been investigated." (PMID 31480312, 2019).
pediatric acute respiratory distress syndrome (1 paper, 2022). "Annotation: PARDS: pediatric acute respiratory distress syndrome; TNF-α, tumor necrosis factor -alpha; IL-6, interleukin-6; IL-1β; IL-17: interleukin-17." (PMID 35506305, 2022).
pemphigus foliaceus (1 paper, 2022). Pemphigus foliaceous is a rare superficial pemphigus disease characterized by multiple, pruritic, scaly, crusted cutaneous erosions, with flaky circumscribed patches, localized mostly on the face, scalp, trunk and extremities, often presenting an erythematous base. "Furthermore, stimulation of PBMC in patients with endemic pemphigus foliaceus resulted in higher IL-1β secretion compared to healthy donors." (PMID 35928825, 2022).